PIK3CA (phosphatidylinositol-4,5-bisphosphate 3-kinase catalytic subunit alpha)
Diseases named in the same sentence as PIK3CA in open-access papers (continued):
Sharing a sentence is not in itself a finding about the gene and the disease.
melanoma (continued). "Mutations found in melanomas on the dorsal hand and foot were reported to be similar to those in melanomas at other sites of intermittently sun-damaged skin, whereas subungual and interdigital melanomas (n = 13) exhibited diverse mutations in PIK3CA, STK11, EGFR, FGFR3, and PTPN11." (PMID 36983205, 2023). "As a potential mechanism of acquired resistance, it has been reported that mutation-specific ctDNA assays allow early detection of the onset of NRAS mutation in patients treated with BRAFi, other than mutations in MAP2K1, AKT1, and PIK3CA in melanoma patients showing treatment resistance." (PMID 37627054, 2023). "We hypothesized that the concomitant targeting of both MAPK and PI3K–Akt pathways in a PIK3CA-mutated melanoma model resistant to BRAF and MEK inhibitors would result in a better therapeutic efficacy that reverts drug resistance mechanisms." (PMID 35335966, 2022). "Of these, one of the most represented PIK3CA mutations (affecting 4% of melanoma patients, according to COSMIC data) with a pathogenetic role in drug resistance is the PIK3CA H1047R mutation associated with both anti-BRAF and anti-MEK inhibitors of drug resistance." (PMID 35335966, 2022). "A previous study in melanoma found that S6K1 inhibition can revert PIK3CA mutation-induced resistance to CDK4/6 inhibitor, while the specific molecular mechanism remained unknown." (PMID 36042494, 2022). "Activating mutations in PIK3CA are also found in some melanomas." (PMID 33549048, 2021). "PIK3CA mutations were detected in 12 melanomas, including 1 tumor with two PIK3CA mutations." (PMID 31277584, 2019). "The aim of this study was to investigate the prevalence and distribution of pathogenetic variants in BRAF, NRAS, and PIK3CA genes among 245 DNA samples from pigmented melanomas of cutaneous origin, defining the fraction of cases harboring coexistent PIK3CA and BRAF or NRAS mutations." (PMID 25627962, 2015). "A melanoma case had NRAS mutation co-occurring with PIK3CA mutation." (PMID 26435479, 2015). "Often melanoma cells with BRAF mutations also contain PTEN or PIK3CA mutations." (PMID 23085539, 2012). "Activating mutations of PIK3CA, which encodes the p110α catalytic subunit of PI3Ks, have been detected with significant frequency in colon, breast, and ovarian cancers, but appear to be rare in melanoma (1.5%)." (PMID 18813315, 2008). "Melanoma-private mutations in genes such as ARID1A, ARID2, PIK3CA, and CDKN2A indicated additional late events contributing to malignant progression." (PMID 41516405, 2026). "These melanoma-private mutations occurred in genes linked to chromatin regulation (ARID1A and ARID2), cell growth (e.g., PIK3CA), cell adhesion (e.g., EPHA2), splicing (SF3B1), angiogenesis (PTPRB), and classic tumor suppressors (NOTCH3, CDKN2A, and PTEN)." (PMID 41516405, 2026). "Due to the higher frequency of loss of PTEN than the oncogenic PIK3CA mutation in melanoma, the significance of the loss of the protein phosphatase activity of PTEN is conceivable in melanoma malignancy." (PMID 38233537, 2024). "PIK3CA mutations are present in head and neck squamous cell cancer (HNSCC), gastric cancer, gallbladder cancer, and melanoma." (PMID 37596643, 2023). "Upon examining the new attention map post the removal of high-attention genes, we discern that the model now places more attention on genes HRAS, AKT2, PIK3CA for melanoma." (PMID 37932419, 2023).
melanoma (continued). "Our results represent proof of a concept that helps us understand the crosstalk existing between the MAPK and PIK3CA pathways that is potentially involved in melanoma drug resistance." (PMID 35335966, 2022). "The major genetic defects identified in the PI3K pathway in melanoma to date have been PTEN deletions and a small number of PIK3CA mutations." (PMID 33549048, 2021). "In some subsets of melanomas, the activating mutations in NRAS, PIK3CA and c-KIT were also related with the hyper-activation of Akt49,50." (PMID 32968045, 2020). "The PREX2 gene plays oncogenic roles in human cancers, such as melanoma, since it is involved in PIK3CA-PTEN-AKT signaling pathway." (PMID 32850962, 2020). "Fisetin has been investigated for treatment cutaneous cancer, particularly melanoma, having constitutive activation of the Akt/mTOR signaling, due to mutations of PTEN, PIK3CA, or TSC1/2." (PMID 31370278, 2019). "In particular, in this study we retrospectively analysed advanced melanomas that had directly progressed from stage IB/II AJCC (American Joint Committee on Cancer) 2017, whose mutational status of BRAF, KRAS, NRAS and PIK3CA genes had already been tested." (PMID 30934988, 2019). "PIK3CA and/or PTEN mutations were least prevalent in pancreatic-cancer samples (3/33; 9%) and melanoma samples (1/11; 9%)." (PMID 29137436, 2017). "In keeping with published studies, there were frequent mutations of BRAF and NRAS in melanoma; BRAF, EGFR, KRAS, and STK11 in NSCLC; APC, BRAF, KRAS, and PIK3CA in CRC; KIT and PDGFR3A in GIST; and CTNNB1 in other tumours (desmoid fibromatosis)." (PMID 28196074, 2017). "The PIK3CA gene was found to be mutated in about 10% of melanomas, and these mutations co-existed with BRAF/NRAS mutations in about 10% of BRAF/NRAS mutant melanomas; on the other hand, about 50% of PIK3CA-mutant melanomas displayed BRAF/NRAS mutations." (PMID 29156643, 2017). "The most frequent melanoma-associated genetic events in PI3K-AKT signaling pathway are inactivating mutations (often related only to exons 9 and 20 of PIK3CA) or PTEN loss of expression or mutations and activating NRAS mutations." (PMID 26863566, 2016). "For instance, PTEN loss is found in 30-50% of melanomas, PIK3CA mutation in 3%, and changes in AKT expression in some melanomas." (PMID 25886620, 2015). "Gene mutation status of BRAF, PIK3CA, PTEN, and hTERT and protein expression of PTEN and pAKT in the melanoma cell line panel." (PMID 26137449, 2015). "A total of 245 tumor specimens (212 primary melanomas and 33 melanoma cell lines) was screened for mutations in BRAF, NRAS, and PIK3CA genes by automated direct sequencing." (PMID 25627962, 2015). "We employed eight cancer cell lines including two melanoma with various mutations such as RAS, RAF, PIK3CA, and PTEN." (PMID 25422890, 2014). "Many established nodal points in the PI3K pathway (i.e. PIK3CA, AKT, PTEN) have been linked to melanoma progression." (PMID 22912864, 2012). "While PIK3CA mutations are more prevalent in colon and breast cancer, BRAF mutation occurs at a high frequency in melanoma." (PMID 19492075, 2009). "In melanoma cells harboring an NRASQ61L or NRASQ61K mutant allele, we find that targeting NRAS alone or both BRAF and CRAF in combination or both BRAF and PIK3CA together showed efficacy." (PMID 19492075, 2009). "Research has demonstrated that patients with melanoma may develop acquired resistance to anti-cancer therapy due to the activation of the PI3K signaling pathway, either as a result of PTEN loss or PIK3CA mutations." (PMID 37096065, 2023). "The overexpression of both PIK3CA wild-type and PIK3CA H1047R was induced in A375 melanoma cells." (PMID 35335966, 2022). "Both PTEN loss and PIK3CA mutations have been shown to increase the rate of melanomagenesis induced by BRAF mutants in genetically-engineered mouse models, which indicates the potential importance of these genetic alterations in melanoma biology." (PMID 33549048, 2021).
melanoma (continued). "S6K1 inhibition may resensitize NRAS-mutant melanoma carrying PIK3CA E545K to combined MEK and CDK4/6 inhibition." (PMID 34804979, 2021). "In this study BRAF, NRAS, KRAS, HRAS, PIK3CA and KIT mutations were examined in melanomas." (PMID 31277584, 2019). "Interestingly, a phase I clinical trial of GDC-0941 in solid cancers showed that a melanoma patient with good response had a BRAF mutation and wild-type PIK3CA." (PMID 27465249, 2016). "The melanoma cell lines had various statuses of the most common mutations in BRAF (BRAFV600E) and NRAS (NRASQ61R), but harboured no mutation in the other key components of the PI3K pathway, including PIK3CA, PTEN, and PIB5PA." (PMID 26573229, 2015). "Metastatic melanomas often express an active form of PIK3CA (p110α); in these cases, p85β upregulation could promote invasion even with limited supply of growth factors." (PMID 25217619, 2014). "Additionally, the BRAF inhibitor vemurafenib is only effective in patients with V600 mutation-positive melanoma, and the phosphoinositide-3-kinase (PI3K) inhibitor GDC-0941 is most effective in preclinical tumor models with PIK3CA mutations." (PMID 23284662, 2012). "Mutations were also identified in brain metastases from non-breast primaries in EGFR (3/9 - 33%; two lung and one kidney), HRAS (1/9 - 11%; lung), KRAS (2/9 - 22%; one colon and one lung), NRAS (3/9 - 33%; two lung and one kidney) and PIK3CA (2/9 - 22%; one melanoma and one lung)." (PMID 20604919, 2010). "Melanomas also harbor mutations that promote the malignant phenotype, such as in BRAF, CDKN2A, PTEN, CTNNB1, NRAS, PIK3CA and KIT, but except for BRAF (∼50%) and common loss of CDKN2A, these mutations exist in a minor portion of melanoma specimens (10% or less)." (PMID 19234609, 2009). "Mutations in PIK3CA are identified in pre-treatment tumor samples of patients who respond poorly to targeted therapy, but their role in generating resistance has not yet been verified in melanoma functional studies." (PMID 35565444, 2022). "However, these associations between genotype and drug response did not necessarily hold, and only some NZM lines with PIK3CA mutations or amplifications were very sensitive to A66, consistent with previous findings in melanoma lines." (PMID 33549048, 2021). "Furthermore, we first studied SNPs rs3730089 in the PIK3R1 gene and rs2699887 in the PIK3CA gene in melanoma patients, observing a trend of worse OS in homozygous recessive patients for the SNP rs2699887 in the PIK3CA gene vs. homozygous dominant and heterozygous genotypes." (PMID 29100280, 2017). "Here, in melanocytes and in melanoma cell lines, we have studied the phosphorylation status of key PKB, mTOR and MAPK pathway components downstream of PTEN, PIK3CA, NRAS and BRAF mutations to determine whether the activity of the signalling pathways correlates with the upstream mutation." (PMID 22475322, 2012). "The clinically characterized tumor molecular subtypes included BRAF, NRAS, KRAS, KIT, and PIK3CA mutant melanomas, with BRAF mutant melanomas being more prevalent in AYA compared to adult patients (77% vs 41%; Fisher’s exact test, P = 0.0003)." (PMID 38589406, 2024). "The most mutated genes, which are associated with the development of resistance to targeted therapy in melanoma include CDKN2A, RB1, PIK3CA, AKT3, HOXD8, PAX5, MAP3K8, and MITF." (PMID 38275910, 2024). "Most relevant molecular drivers that participate to melanoma metabolic plasticity include AKT, BRAF, p14ARF, MYC, NRAS, phosphatidylinositol-4,5-bisphosphate 3 kinase catalytic subunit α (PIK3CA) and phosphatase and tensin homolog (PTEN)." (PMID 32528879, 2020).
melanoma (continued). "The spectrum of genomic alterations in melanoma involve multiple genes and signaling networks, but the most frequently altered pathways are MAPK, PIK3CA, KIT signaling, and apoptosis/cell senescence pathways." (PMID 32850962, 2020). "Our results showed that THOC2 inhibition significantly reduced the expression of PDE4D, PIK3CA, GNAI1, ADCY1, HHIP and ADORA2A in melanoma cells." (PMID 31680623, 2019). "THOC2 expression was positively correlated with PDE4D, PIK3CA, GNAI1, and HHIP expression in melanoma tissues." (PMID 31680623, 2019). "In fact, in melanomas, hotspot regions or amplification of KIT, PIK3CA, MITF and CTLA4 are often analyzed." (PMID 26863566, 2016). "The frequency of mutations in the genes is consistent with that reported in the literature for IDH1 and IDH2 in brain tumors, EGFR and KRAS in NSCLCs, KRAS and NRAS in CRCs, BRAF, RAS, PIK3CA, and TERT in thyroid nodules, BRAF, NRAS and cKIT in melanoma, and KRAS in pancreatic pre-operative samples." (PMID 32340363, 2020). "In addition, correlation analysis showed that THOC2 expression was correlated with PDE4D, PIK3CA, GNAI1, and HHIP expression in melanoma tissues." (PMID 31680623, 2019). "NGS revealed 118 (26%) of 446 melanomas with no mutation, 42% with BRAF mutations, 25% with NRAS mutations, 4.9% with KIT mutations, and 2.0, 2.7 and 2.7% with HRAS, KRAS and PIK3CA mutations, respectively." (PMID 31277584, 2019). "Nowadays limited data have been published about the SNP rs2699887 in the PIK3CA gene and it has not been investigated in melanoma patients so far." (PMID 29100280, 2017). "Targeting both the RAS-effector arms, either by combined BRAF and PIK3CA or MEK1+2 and PIK3CA together, effectively delayed the tumor growth confirming the importance of both the PI3K and RAF effector arms in the IPC298 NRAS-mutant melanoma line for tumor growth." (PMID 19492075, 2009). "Although, we did not identify any melanoma cell lines with PIK3CA activating mutations in the GDSC database, these data indicate that activating RAS mutations and loss-of-function NF1 or PTEN mutations do not diminish the sensitivity of melanoma cell lines to MEK inhibition in vitro." (PMID 30237495, 2018). "We now show, that PI3K/AKT signalling via potent oncogenic PIK3CA and AKT3 mutants, is not sufficient to overcome proliferative arrest induced by BRAF/MEK inhibition, but rather enables the survival of a dormant population of MAPK-inhibited melanoma cells." (PMID 30237495, 2018).
glioma (106 papers, 2009 to 2025). A benign or malignant brain and spinal cord tumor that arises from glial cells (astrocytes, oligodendrocytes, ependymal cells). "Overall, studies point to a potential important role of PIK3CA mutations in glioma, but the current body of evidence remains inconsistent." (PMID 40508087, 2025). "The frequency and impact of oncogenic PIK3CA mutations has also been explored in glioma, yet questions remain about their true relevance in this context." (PMID 40508087, 2025). "Genetic alterations, such as PTEN loss and PIK3CA amplification, contribute to its hyperactivation in gliomas." (PMID 41270054, 2025). "In gliomas, however, studies have reported inconsistent PIK3CA mutational frequencies, ranging from 0% to 30%." (PMID 40508087, 2025). "Research regarding PIK3CA mutation frequencies in lower-grade glioma has been similarly inconclusive, with mutation rates reported from 0% to 14% depending on the histological subtype and methodology used." (PMID 40508087, 2025). "As such, much remains to be explored regarding the potential of PIK3CA mutations as biomarkers in glioma." (PMID 40508087, 2025). "In our study, we identified PIK3CA mutations in only two of the 25 patients with low-grade glioma, both of whom were resistant to antiseizure medications." (PMID 40103938, 2025). "Wang and colleagues reported that patients with PIK3CA-mutated lower-grade gliomas had significantly lower overall and progression-free survival than patients with wildtype tumors." (PMID 40508087, 2025). "In gliomas, however, the role of PIK3CA mutations in modulating sensitivity to PI3K pathway inhibition remains poorly understood." (PMID 40508087, 2025). "Although several studies have examined the frequency of PIK3CA mutations in glioma, most were mainly based on outdated histological classifications, with few considering the updated molecularly defined subgroups." (PMID 40508087, 2025). "While most studies have focused primarily on PIK3CA mutational frequencies, there has been limited research into their impact on prognosis and therapy response in glioma, which remains poorly understood." (PMID 40508087, 2025). "In this review, we examine the clinical relevance of PIK3CA mutations across different cancers, with a particular focus on their emerging role in glioma." (PMID 40508087, 2025). "Still, none of these studies have analyzed the effect of PI3Kα selective isoform inhibitors specifically in PIK3CA-mutated glioma." (PMID 40508087, 2025). "While clinical data on the prognostic relevance of PIK3CA mutations in glioma continues to grow, research into their underlying pathogenic mechanisms remains scarce." (PMID 40508087, 2025). "Phosphatidylinositol-4,5-bisphosphate 3-kinase catalytic subunit alpha (PIK3CA) activating mutations have recently shown great promise as potential therapeutic targets in glioma." (PMID 40508087, 2025). "In lower-grade gliomas, the prognostic value of PIK3CA mutations has been explored to a limited extent." (PMID 40508087, 2025). "In a retrospective analysis involving 134 glioma patients with PIK3CA variants, the presence of the H1047R mutation was associated with poorer seizure control." (PMID 39201639, 2024). "Specific variants in the PIK3CA gene have been associated with peritumoral hyperexcitability and seizures in glioma patients." (PMID 39201639, 2024). "Glioma-specific mutations in PIK3CA have been implicated in seizure onset, with glypican-3 (GPC3) emerging as a driver of synaptogenesis and hyperexcitation." (PMID 38193532, 2024). "Given the prevalence of PIK3CA mutations in glioma tumors, we initiated an analysis of the association between CBX2 and PIK3CA mutations using TCGA datasets." (PMID 39114365, 2024). "The PI3K pathway is frequently activated in gliomas, particularly higher-grade gliomas, due to gain-of-function mutations in the PIK3CA gene or loss of the tumor suppressor PTEN." (PMID 39201639, 2024).